TNF (tumor necrosis factor)
Diseases named in the same sentence as TNF in open-access papers (continued):
Sharing a sentence is not in itself a finding about the gene and the disease.
Abdominal obesity (continued). "Visceral adipocytes stimulate the production of several cytokines, including interleukin-6 and tumor necrosis factor-alpha, in patients with abdominal obesity, which encourages macrophage infiltration and persistent inflammation." (PMID 39511357, 2024). "In patients with abdominal obesity, visceral adipocytes induce synthesis of a variety of cytokines like interleukim-6 and tumor necrosis factor-α, which promote macrophage infiltration and chronic inflammation." (PMID 35027066, 2022). "But Park (2015) examined the effect of combined exercise on postmenopausal women with abdominal obesity and concluded that after 12 weeks of combined exercise, visceral fat and TNF-α reduced." (PMID 34742317, 2021). "The result showed that central obesity lowers adiponectin plasma levels via increasing proinflammatory adipokines, such as TNF-alpha, leptin, and IL-1β." (PMID 33946540, 2021). "The reduction of high-density lipoprotein cholesterol (HDL-C) suppresses osteogenic activity in vascular cells, and abdominal obesity increases inflammatory cytokines such as interleukin-6 (IL-6) and tumor necrosis factor alpha (TNF-α)." (PMID 31341843, 2019). "Some studies indicated that gene expression and production of IL-6 and TNFα are elevated in general and abdominal obesity." (PMID 31272370, 2019). "Our findings revealed that hypertensive women with central obesity had a lower anti-inflammatory status (adiponectin) and a higher pro-inflammatory status (TNF-α) than obese alone or hypertensive alone women." (PMID 29636702, 2018). "Our results indicated that the concentration of pro-inflammatory adipokine TNF-α was higher in hypertensive women with central obesity than hypertensive or obese alone women." (PMID 29636702, 2018). "General obesity was associated with significantly elevated levels of IL-5, IL-10, IL-12, IL-13, IFN-γ and TNF-α, central obesity with significantly elevated IL-5, IL-10, IL-12, IL-13 and IFN-γ-levels." (PMID 25781614, 2015). "The strong positive association between TNF-α and waist circumference observed in our study directly supports the adipose-inflammation connection, consistent with meta-analyses demonstrating robust correlations between TNF-α and central obesity." (PMID 41590632, 2025). "Individuals with abdominal obesity often exhibit high levels ofproinflammatory cytokines (tumor necrosis factor-α (TNF-α), interleukin-1α (IL-1α), interleukin-1β (IL-1β), interleukin-6 (IL-6)and interleukin-8 (IL-8)), which can be considered significant prognostic indicators of CVD risk." (PMID 39076338, 2024). "The exercise-induced reduction in abdominal obesity resulting from the metabolically active visceral adipocytes may also lead to reduced secretions of tumor necrosis factor-alpha (TNF-α) and IL-6." (PMID 38540173, 2024). "In abdominal obesity, visceral fat produces pro-inflammatory cytokines, known as adipocytokines, including leptin, resistin, visfatin, interleukin 6 (IL-6), and tumor necrosis factor α (TNF-α), which influence systemic inflammation and insulin sensitivity." (PMID 39767613, 2024). "Interestingly, concentrations of TNF‐α were similar between WEs with central obesity and SAs who were lean, as were numbers of IM and NCM." (PMID 38011590, 2023). "Additionally, leptin, adiponectin, resistin, TNF-α, IL-6, and other metabolic substances are related to the relationship between abdominal obesity and BMD." (PMID 36313427, 2022). "Thus, individuals with central obesity had increased pro-inflammatory adipokines (TNF-α, leptin) and decreased anti-inflammatory adipokines (adiponectin), compared to individuals without central obesity." (PMID 33182462, 2020). "Therefore, this study sought to determine the role of adipokines (adiponectin, plasminogen activator inhibitor-1, leptin, and tumor necrosis factor-α) in hypertensive Hong Kong Chinese women with central obesity." (PMID 29636702, 2018).
Abdominal obesity (continued). "Therefore, this study was designed to determine the role of adipokines (adiponectin, plasminogen activator inhibitor-1, leptin, and TNF-α) in hypertensive Hong Kong Chinese women with established central obesity." (PMID 29636702, 2018). "In obese adolescent girls, TNF-α, IL-4 and IL-5 levels were higher in those with central obesity." (PMID 25781614, 2015). "We proposed that abdominal obesity might contribute to increase the tumor necrosis factor-α (TNFα) and FFA levels in the liver and that these factors could induce oxidative and nitrosative stress." (PMID 25261569, 2014). "In particular, the altered pattern of adipocytokine secretion characterizing central obesity—that is, reduced adiponectin and elevated levels of leptin, resistin, TNFα, and IL-6—increases the production of superoxide anion (O2−), that interferes with NO availability, thus reducing vasodilation." (PMID 20652043, 2010). "Further studies are needed to understand the relationship between TNF-α and central obesity." (PMID 18289377, 2008). "Moreover, after adjustment for age, BMI, and gender, the levels of TNF-α, IL-6, and ROS were associated with central obesity but not general obesity." (PMID 25918477, 2015). "Besides being strongly related with body mass index (r = 0.5154), serum IL-12 exhibited a significant relationship with abdominal obesity (r = 0.4481), body fat percentage (r = 0.5625), serum glucose (r = 0.3158), triglyceride (r = 0.3714), and TNF-α (r = 0.4717)." (PMID 23533314, 2013). "The correlation between TNF-α and fat percentage (FAT%) (r = 0.278, p < 0.001), as well as waist circumference (r = 0.200, p = 0.008), highlights its role in promoting abdominal obesity and central fat accumulation." (PMID 40137151, 2025). "Among them, adiponectin, leptin, TNF-α, Factor D (adipsin), lipocalin-2 (NGAL), Serpin E1 (PAI-1), and CXCL8 (IL-8) were confirmed to have a positive correlation with central obesity (defined as WC)." (PMID 36768360, 2023). "Respondents with abdominal obesity had higher levels of TNF-α, and positive correlations were found between TNF-α and BMI in women." (PMID 37375693, 2023). "In a small group of patients with abdominal obesity HDL cholesterol correlated inversely not only with resistin but also visfatin, and TNF-α." (PMID 28771611, 2017). "Our results showed that serum adipokines, including visfatin, resistin and TNF-α, correlated inversely with serum HDL cholesterol level in patients with abdominal obesity." (PMID 27468698, 2016). "High levels of inflammatory markers such as IL-6, tumor necrosis factor, and CRP are related to general and abdominal obesity." (PMID 25874126, 2015). "However, a study comparing EPA (2.7 g) and DHA (2.7 g) in individuals with abdominal obesity and low-grade systemic inflammation found lowering of CRP, IL-6, IL-18, and TNF, where DHA was more potent than EPA." (PMID 40058591, 2025). "It has been proposed that in central obesity, white adipose tissue is infiltrated by activated macrophages (M1) and correlates with secreting monocyte chemoattractant protein-1 (MCP-1), tumor necrosis factor α (TNFα), interleukin-1β (IL-1β), interleukin 6 (IL-6), and interleukin 1α (IL-1α)." (PMID 40002817, 2025). "In abdominal obesity, visceral fat deposits become enlarged and dysfunctional and produce inflammatory biomarkers like C-reactive protein (CRP), cytokines, tumor necrosis factor-alpha (TNF-a), prostaglandins, and leptin." (PMID 40278381, 2025). "Studies have shown that central obesity/VAT is related to dysregulated adipokine secretion, with increased levels of plasminogen activator inhibitor (PAI-1), tumor necrosis factor-alpha (TNF-α), monocyte chemotactic protein-1 (MCP-1), angiotensinogen, and interleukin 6 (IL-6)." (PMID 35276815, 2022). "Furthermore, in postmenopausal women with central obesity, both the Central European diet and the Mediterranean diet intervention for 16 weeks resulted in reduced TNF transcription and lower blood TNF-α contents." (PMID 36615742, 2022).
Abdominal obesity (continued). "Although abdominal obese women had higher C-reactive protein and fibrinogen plasma levels at the baseline, these are not good markers of abdominal obesity such as IL-6, TNF-α, and TNF-β." (PMID 30107482, 2019). "The exercise group's abdominal obesity was mitigated due to visceral fat reduction; grip strength, push-ups, and oxygen uptake per weight improved; and HDL-C and IgA level also increased, while TNF-α, CD14, and endotoxin levels decreased." (PMID 26075288, 2015). "In addition, eotaxin, TNF-α, and interleukins 4 and 5 levels have previously been found to be elevated in the broncho-alveolar lavage fluid (BALF) of obese mice, particularly in those with central obesity." (PMID 37730940, 2023). "We hypothesized that habitual dietary fat intake, the IL6 genotype, and MED or the CED for 16 weeks would affect selected biomarkers of inflammation (TNFα and IL6) in postmenopausal women with central obesity; the obtained results partly confirm this hypothesis." (PMID 31295854, 2019). "Abdominal obesity promotes increased secretion of a range of metabolites and of biologically active substances, including glycerol, FFA, inflammatory mediators (e.g. tumor necrosis factor alpha (TNFα) and interleukin-6 (IL-6)), plasminogen activator inhibitor-1 (PAI-1) and C-reactive protein." (PMID 24410812, 2014).
osteosarcoma (102 papers, 1995 to 2025). A usually aggressive malignant bone-forming mesenchymal neoplasm, predominantly affecting adolescents and young adults. "In osteosarcomas, elevated levels of cytokines IL-6 and TNF-α have been linked to more aggressive disease, including metastasis and reduced survival." (PMID 40506947, 2025). "In osteosarcoma metastasis, genes associated with chemokine activity, chemokine receptor binding, and the TNF signaling pathway are enriched, and KIFC3 has been identified as a significant prognostic biomarker." (PMID 40299423, 2025). "Other authors indicated that IL-6, IL-8 and TNF-α are associated with an increased risk of osteosarcoma, and that elevated levels of IL-8 and TNF-α are correlated with the progression of this disease." (PMID 40722593, 2025). "Tumor necrosis factor-alpha (TNF-α) rs361525 was significantly associated with decreased risk of osteosarcoma under the heterozygous model (the only model investigated due to unavailability of allele frequency), GA vs GG: OR 0.53 95% CI = 0.28–0.98, P = 0.04." (PMID 38360742, 2024). "It is suggested to be implicated in osteosarcoma initiation and metastasis through upregulating the level of IL-6 and TNF-α." (PMID 34804118, 2021). "We would predict that Smac mimetic treatments would be ineffective in osteosarcoma-bearing animals treated with TNFα-blocking agents, or TNFα-deficient mice." (PMID 31521127, 2019). "Lethal tumorigenesis of AX osteosarcoma cells was completely abrogated in TNFα-deficient mice and IL-1a/IL-1b doubly deficient mice, which occurred through ERK activation." (PMID 28115942, 2016). "On the other hand, studies on a mouse model using osteosarcoma cell line AX have shown that TNF by tumor-associated macrophages and IL-17 produced by CD4+ lymphocytes maintain osteosarcoma cells in an undifferentiated state by inhibiting their osteoblastic differentiation." (PMID 39060500, 2024). "Indeed, the presumed deficiency in TNFα-producing tumor-associated myeloid cells within SCID mice probably explains the relatively poor anti-osteosarcoma efficacy of LCL161 in treating SCID mice bearing patient-derived xenografts." (PMID 31521127, 2019). "That study suggested that the TNF-238G>A was inversely associated with osteosarcoma." (PMID 21437228, 2011). "Cytokine profiling has identified inflammatory mediators such as IL-1Ra, IL-6, IL-8, and TNF-α as prognostic indicators in osteosarcoma, with distinct cytokine endotypes correlating with metastatic risk and survival outcomes." (PMID 40506947, 2025). "TNF-α, in particular, is a potent NF-κB activator and has been demonstrated to protect osteosarcoma cells from apoptosis by enhancing the expression of anti-apoptotic proteins like Bcl-2 and cIAPs." (PMID 39949765, 2025). "Pro-inflammatory cytokines, such as IL-6 and TNF-α, promote tumor cell survival by activating anti-apoptotic pathways, thereby increasing osteosarcoma cells’ resistance to therapeutic interventions." (PMID 39949765, 2025). "IFIT2, a key mediator of the TNF/NF-κB signaling pathway, plays a critical role in osteosarcoma progression." (PMID 40426910, 2025). "Increased IFIT2 levels activate the TNF/NF-κB pathway—a pivotal driver of osteosarcoma—resulting in enhanced cell proliferation, suppressed apoptosis, and heightened invasive and metastatic capacities." (PMID 40426910, 2025). "Similar to CRP, elevated ESR is likely driven by proinflammatory cytokines such as IL-6 and TNF-α, which are known to play a role in osteosarcoma pathogenesis." (PMID 40926779, 2025). "TNF-α, another essential pro-inflammatory cytokine, contributes to the maintenance of chronic inflammation in the osteosarcoma TME." (PMID 39949765, 2025). "In osteosarcoma, NF-κB regulates two crucial cytokines: interleukin-6 (IL-6) and tumor necrosis factor-alpha (TNF-α)." (PMID 39949765, 2025).
osteosarcoma (continued). "Knockout studies of ADCK2 in prostate and osteosarcoma cells have demonstrated a reduced impact of tumor necrosis factor-alpha (TNFα) on hypoxia-inducible factor 1-alpha (HIF-1α), suggesting a potential role for ADCK2 in hypoxia-driven tumor progression." (PMID 40565246, 2025). "The dataset GSE99671 provides RNA-sequencing results of osteosarcoma tissues and normal bone samples, with which we analyzed differentially expressed genes and found that SQLE was upregulated (p = 0.0087) but TNF was downregulated (p > 0.05) in osteosarcoma." (PMID 38338920, 2024). "The pooled ORs of 12 variants in 8 genes (CTLA-4, ERCC3, IL-8, PRCKG, RECQL5, TNF-α, XRCC3, and VEGF) were significantly associated with the risk of osteosarcoma in the main analysis." (PMID 38360742, 2024). "Our main analysis identified significant associations with osteosarcoma for 12 variants in 8 genes: CTLA-4, ERCC3, IL-8, PRCKG, RECQL5, TNF-α, XRCC3, and VEGF." (PMID 38360742, 2024). "The findings suggested that inhibitory effects of IL-17 and TNF on osteoblastogenesis contribute to osteosarcoma progression." (PMID 39060500, 2024). "In prior meta-analyses, associations of genetic polymorphisms in VEGF, MDM2, CTLA-4, TNF-a, TNF-b1, PRCKG, RECQL5, XRCC3, and GST with osteosarcoma susceptibility were investigated." (PMID 38360742, 2024). "Cell–cell communication analysis indicates that ZFP36L2 targets TNF in IL1β+ osteosarcoma, thereby improving prognosis." (PMID 39767767, 2024). "The GSVA showed an increase of IFN‐α response, IFN‐γ response, and TNF–α signaling via NF‐κB in post‐NACT osteosarcoma, suggesting an activation of antitumor immune responses after NACT." (PMID 37457661, 2023). "It promotes apoptosis through the action of TNF-α and nuclear factor κB, thereby affecting osteosarcoma cell proliferation, cell cycle, and apoptosis, providing a candidate molecular target for osteosarcoma prevention and treatment." (PMID 35242717, 2022). "The cytokines VEGF, IL-17, IL-6, IL-8, IL-1Ra, TNF-α, and IL-34 can promote the proliferation of osteosarcoma cells, and TGF-β exerts dual effects on tumors; they inhibit tumor growth in the early stage and promote tumor growth in the late stage." (PMID 35102149, 2022). "Among these, VEGF, IL-17, IL-6, IL-8, IL-1Ra, TNF-α, and IL-34 can promote cell proliferation in osteosarcoma; only TGF-β has a dual role in the tumor." (PMID 35102149, 2022). "RNA-Seq of KDM5A-KO cells indicated that interferon, epithelial–mesenchymal transition (EMT), IL6/JAK/STAT3, and TNF-α/NF-κB pathway were likely involved in the regulation of osteosarcoma cell viability." (PMID 33436536, 2021). "The data presented herein show that TNF-armed MYXV is a viable treatment strategy for metastatic osteosarcoma, as evidenced in a murine model where unarmed MYXV constructs have failed." (PMID 34553039, 2021). "We conclude that systemic ex vivo virotherapy with TNF-α-armed MYXV represents a new potential strategy against lung metastatic cancers like osteosarcoma and can potentially act synergistically with established checkpoint immunotherapies." (PMID 34553039, 2021). "LncRNA THRIL has also been shown to regulate TNF-α expression and participate in immune response in osteosarcoma." (PMID 34692688, 2021). "In this study, leukocytes are used to deliver TNF-α-armed myxoma virus to lung metastatic osteosarcoma tumors." (PMID 34553039, 2021). "RBM10 overexpression induced osteosarcoma cell apoptosis via the inhibition of Bcl-2, the activation of caspase-3, and the transcription and production of TNF-α." (PMID 34804951, 2021). "In this study, we assessed MYXV armed with human TNF (vMyx-hTNF) in the K7M2-Luc (luciferase-expressing murine osteosarcoma K7M2 cells derived from the BALB/c lineage) syngeneic lung metastatic osteosarcoma model in BALB/c mice." (PMID 34553039, 2021).